AFP (alpha fetoprotein)
Diseases named in the same sentence as AFP in open-access papers (continued):
Sharing a sentence is not in itself a finding about the gene and the disease.
tumor (continued). "A bioinformatic analysis of the transcriptome databasesof patients with various oncological diseases revealed that a high level ofDENR expression in tumor cells correlates with a high serumlevel of alpha-fetoprotein." (PMID 34377560, 2021). "In the multivariable analysis, six variables were identified as risk factors for HCC-related death: sex, ln (AFP+1), ln (PIVKAII), PET positivity, largest tumor size (mm), and NLR." (PMID 34203396, 2021). "As the spheroids were AFP-positive tumor cells, fresh CAF isolates from 3 HCC patients were analyzed by fluorescence-activated cell sorting (FACS) for contaminating non-CAF cells." (PMID 34947582, 2021). "The high tumor load and AFP values at baseline of these 3 patients together with extrahepatic and macrovascular spread at the inception of the study indicates a more advanced disease state before treatment." (PMID 34850325, 2021). "Significant prognostic factors for OS were maximum tumor diameter, tumor number, extension of mPVTT, and AFP." (PMID 34513667, 2021). "Other pathological features and tumor markers such as tumor differentiation, tumor size, and AFP level are also used in the survival assessment of HCC patients." (PMID 34840628, 2021). "We retrospectively collected 1153 patients who underwent liver resection for HCC, and our multivariate analysis revealed preoperative total tumor volume (TTV) and alpha-fetoprotein (AFP) to be independent risk factors for MVI." (PMID 34503212, 2021). "In univariate analysis, elevated AFP levels and larger tumor sizes (>30 mm) were found in the MVI positive group (both p<0.05) of the training population." (PMID 34307168, 2021). "To explore the impact of the baseline bias, we performed stratification analyses in subgroups on our developed DL models regarding tumor size, AFP and hepatic function." (PMID 34068972, 2021). "High AFP levels indicate that the tumor is highly aggressive; the probability of intra-hepatic metastasis is usually greater in patients with high AFP levels." (PMID 33726693, 2021). "The tumor parameters, including tumor size, number, AFP level, tumor grade, microvascular infiltration and preoperative downstage treatment, were consistent between the two groups in our study." (PMID 34966679, 2021). "Preoperative AGLR level was positively correlated with alpha-fetoprotein (AFP), tumor size, tumor-node-metastasis (TNM) stage, and microvascular invasion (MVI) (all p < 0.05)." (PMID 33536005, 2021). "On receiver operator curve (ROC) analysis, tumor size 3.7 cm (AUC = 0.68, P = 0.003) and AFP level of 600 ng/ml(AUC = 0.7, P = 0.001) were significant for recurrence." (PMID 34295467, 2021). "The statistically significant factors were Child–Pugh score, WBC, AST, serum AFP > 400 ng/mL, tumor size, and TACE+." (PMID 33436856, 2021). "Cox multivariate analysis revealed several risk factors for OS as follows: multiple tumors (P < 0.001), AFP ≥400 ng/ml (P = 0.001), tumor diameter ≥5 cm (P = 0.022), microvascular invasion (P = 0.003) and high NET1 expression (P = 0.007)." (PMID 33839702, 2021). "The system refined the individual prognostic variables with age and the PRETEXT stage, together with annotation factors, alpha-fetoprotein (AFP) concentration, metastases, and tumor resectability." (PMID 33937051, 2021). "Among the tumor markers, alpha fetoprotein (AFP) was significantly elevated (1,649.0 μg/L), carbohydrate antigen 125 (CA125) was sightly increased (113.0 kU/L), and carcinoembryonic antigen (CEA) and carbohydrate antigen 199 (CA199) were normal." (PMID 35187075, 2021). "In agreement with our findings, HMGCS2 was previously reported to be significantly down-regulated in HCC patients with high alpha-fetoprotein (AFP), tumor size >5 cm, multinodular, advanced tumor staging including BCLC, TNM and CLIP." (PMID 34830779, 2021). "We observed that a high replication stress signature was closely related to the presence of tumor thrombus, high AFP level, advanced BCLC stage, and advanced TNM stage." (PMID 34663432, 2021).
tumor (continued). "ZFHX3, Zinc Finger Homeobox 3, was first identified as a suppressor of alpha-fetoprotein gene and is a tumor suppressor in several cancers." (PMID 33479213, 2021). "Incorporating tumor diameter, AFP and TB, the nomogram achieved a better concordance index of 0.725 (95%CI: 0.661–0.788) in predicting MVI presence." (PMID 34234239, 2021). "Accordingly, a recently proposed dropout calculation from patients on the waiting list comprises the Child-Pugh score, number of tumor lesions, AFP value, and the MELD score." (PMID 33801887, 2021). "Serum analysis showed significantly increased AFP values at 816.2 ng/mL (normal <5.0 ng/mL), whereas the remaining tumor markers were in the normal range." (PMID 33607799, 2021). "Most patients' AFP or PIVKA-II values were elevated at the time of tumor rupture or tumor aggravation." (PMID 34733878, 2021). "In the training cohort, clinical information (larger tumor size, higher AFP level) and CEUS LR-M were significantly correlated with the presence of MVI (all p<0.05)." (PMID 34307168, 2021). "Apart from tumor morphology and AFP, the liver tumor microenvironment also determines tumor biology and aggressiveness." (PMID 33670174, 2021). "In the univariate analysis for DFS, variables with P < 0.1 including sex, age, portal vein invasion, ascites, AFP, tumor capsule, tumor size, tumor number, MVI, cell differentiation, MKI, NLR, PLR, GPR, ALR and FAR were selected for the multivariate analysis." (PMID 34535132, 2021). "All these scores mainly include tumor size, tumor number, and alpha fetoprotein as surrogates for the tumor burden and remnant liver function." (PMID 34638502, 2021). "One particular approach has been development of flexible models using various combinations of tumor size, number and AFP levels." (PMID 34295467, 2021). "Largest tumor diameter, tumor number, mPVTT extension, and AFP values have independent impacts on patients’ OS." (PMID 34513667, 2021). "Total of 5 independent risk factors were identified, including preoperative blood AFP level, preoperative HBeAg status, MVI classification, largest tumor diameter and the status of serosal invasion." (PMID 34229698, 2021). "Subjects who achieved LTC had less advanced BCLC stage, had with fewer treated tumor lesions of a smaller dimension, had a lower percentage of patients with baseline alpha-fetoprotein (AFP) concentration below 200 ng/mL and lower baseline AST level." (PMID 34685433, 2021). "Extended selection criteria, beyond the original Milan criteria for choosing LT as the treatment of choice, have been in practice at many centers the world over, the latest being the total tumor volume (≤115 cm3)/AFP ≤400 ng/mL (TTV/AFP) model." (PMID 34754704, 2021). "In our study, tumor diameter and AFP were the independent MVI prognostic factors, consistent with previous studies." (PMID 34234239, 2021). "Turning to tumor markers, in a study of 209 cases in Japan, the α-fetoprotein (AFP) positivity rate was about 50% (AFP 10–100 ng/mL, 27.9%; ≥100 ng/mL, 20.6%), accompanied by an abnormal prothrombin [des-gammacarboxy prothrombin (DCP)]." (PMID 33572797, 2021). "We noticed the improvement of MVI detection under SPRING was more significant in tumor size ≧5.0 cm group and AFP ≧400 group (67.9 vs. 20.5%, P<0.001)." (PMID 34804920, 2021). "Five variables employed by the nomogram included one clinical factors (AFP level) and four MR imaging features (tumor number, arterial peritumoral enhancement, satellite nodule and peritumoral hypointensity at HBP)." (PMID 34094938, 2021). "A multiple Cox proportional hazard model for death was calculated for our HCC patients on common liver function tests, blood count, and HCC parameters (PVT, tumor multifocality, and serum AFP levels)." (PMID 33546234, 2021). "RBP-score effectively predicted the overall survival (OS) and disease-free survival (DFS) of HCC patients and was associated with the tumor, node, metastasis (TNM) stage, α-fetoprotein (AFP), and metastasis risk." (PMID 35036125, 2021).
tumor (continued). "Based on the origin, the types of AFP include natural AFP (nAFP), which is derived from fetal cells, and tumor-derived AFP (tAFP), which is highly expressed in HCC and other cancers." (PMID 33898423, 2021). "Alpha-fetoprotein (AFP)-producing adenocarcinoma from the gastrointestinal tract (APA-GI) is a rare type of highly malignant tumor with a poor prognosis." (PMID 33996549, 2021). "BWS patients should undergo routine tumor surveillance with abdominal/renal ultrasounds and the serial dosage of serum alpha-fetoprotein (AFP), even if its utility is still debated." (PMID 33810554, 2021). "We acknowledge the following four limitations: First, due to the small number of positive results in each tumor marker test, we cannot yet determine which specific tumor marker (t-PSA, AFP, CEA, CA125, or CA199) is associated with tongue fur thickness." (PMID 34887933, 2021). "We found that one patient had tumor with CR, while the AFP level was increased, indicating the possible progression in the future." (PMID 34136374, 2021). "On the other hand, AFP increases with hepatocyte regeneration, such as in cases of liver inflammation, reducing the specificity of AFP as a tumor marker." (PMID 34681709, 2021). "To minimize the effect of confounding factors, we performed PSM analysis using the following factors: age, sex, etiology, ALBI score, tumor size, tumor number, AFP value, and DCP value." (PMID 33466496, 2021). "Although plenty of tumor antigens have been found in liver cancer, only the vaccines targeting AFP, GPC3 and MRP3 show good tolerance and safety, and the specific T cell response rate of these vaccines exceeds 70%." (PMID 34513678, 2021). "Type of PVTT (P=0.004), INR level (P<0.001), AFP (P<0.001), tumor encapsulation (P<0.001), and aspartate aminotransferase (P=0.011) were independent predictors of RFS." (PMID 34395264, 2021). "In multivariate analysis, tumor burden including tumor size and high AFP level determined the PFS and OS." (PMID 34503135, 2021). "The tumor size, number, histological grade of differentiation, microvascular and macrovascular invasion, alpha-fetoprotein level, and ischemia time are proved as the predictors of HCC recurrence after OLT." (PMID 33964921, 2021). "Among tumor markers, age-related increases in RVs (SDRage≥0.4) was observed in both sexes for AFP, in males for CA19-9, and in females for CEA and CA15-3, while age-related reduction was observed for CA125 in females." (PMID 33411740, 2021). "Repeat imaging demonstrated a significant increase in the size of the tumor, and his germ cell markers were notable for an interval increase in his serum AFP level." (PMID 36284916, 2021). "An approach to risk stratification for early recurrence of HBV-related HCC was developed by incorporating serum AFP, tumor number, and largest tumor diameter based on the Chinese population." (PMID 34676160, 2021). "The tumor number and size, the preoperative alpha-fetoprotein (AFP) level, the preoperative albumin-bilirubin (ALBI) grade and gender were first combined as independent predictors to first validate the pre-ERASL model." (PMID 33924061, 2021). "The current study built on the previous work as it analyzed the cumulative impact of TBS (i.e., metric of tumor morphology) and serum AFP levels (i.e., metric of tumor aggressiveness) among patients with resectable HCC." (PMID 33670174, 2021). "On the other hand, extracellular AFP promotes tumor cells to secrete ligands such as Fas-L, while intracellular AFP promotes the expression of surface antigens such as PD-L1 and B7-H4, so as to achieve the role of immune escape." (PMID 34680245, 2021). "In the logistic regression analysis, the only factors predicting the inability to ever achieve tumour downstaging were pretreatment AFP > 1000 ng/mL and Child–Pugh B/C." (PMID 34944957, 2021). "The positive rate of AFP in APA-GI tumor tissue was 36.4%, and it was partly expressed in hepatoid differentiated tissue." (PMID 33996549, 2021).
tumor (continued). "Other approaches investigate the contribution of tumor markers like α-fetoprotein (AFP) and molecular markers derived from the tumor or adjacent non-tumor samples." (PMID 33562173, 2021). "The French Liver Transplantation Study Group suggested incorporating AFP to tumor size and number to better identify appropriate candidates for liver transplantation." (PMID 33670174, 2021). "Alpha fetoprotein (AFP) as a specific tumor marker not only plays an important role in the diagnosis of HCC, but also be used to assess tumor burden, which is why it is used to predict prognosis in patients with HCC after various treatments." (PMID 34976804, 2021). "Sequential follow-up with testing for tumor markers (β-hCG and AFP) and vaginal ultrasound was recommended." (PMID 34053459, 2021). "Our data does further suggest that staging systems incorporating biochemical markers of tumor biology (AFP) provide more solid estimates for OS in surgical patients than staging systems focusing on radiological characteristics only." (PMID 33294952, 2021). "In the PSM cohort, LLL, multiple tumors, tumor size >10 cm, presence of macrovascular invasion, and PRO AFP ≥400 ng/ml were considered significant risk factors (p < 0.05) for OS in univariate analysis." (PMID 33932132, 2021). "Tumor size, tumor number, AFP level, and percentage of patients within Milan or UCSF criteria were not significantly different between types of OLT." (PMID 34188156, 2021). "High alpha-fetoprotein (AFP) (9/22) and a large tumor size (4/22) were both frequently detected clinical risk factors for MVI prediction." (PMID 34831018, 2021). "In contrast, the AFP-specific T cell response showed correlations with different tumour characteristics opposite to those of the CTA/SALL4-specific T cell response." (PMID 34496797, 2021). "The results showed that AFP level, TNM staging, tumour size and ACLY expression level were independent risk factors affecting the overall survival rate of HCC patients." (PMID 33393219, 2021). "Tumor markers of AFP and β-HCG can be used as the basis for patient diagnosis, follow-up observation, and determination of malignant recurrence of FIF." (PMID 34109141, 2021). "Collectively, the data from the current study highlight the importance of both tumor morphology and serum AFP levels to predict outcomes of patients undergoing resection of HCC." (PMID 33670174, 2021). "AFP and ICAM-1 have multiple biological functions, for example, recent studies have reported that AFP not only plays a biological role as a tumor marker but also has the ability to regulate cell proliferation, differentiation, and tumorigenesis." (PMID 34696675, 2021). "Mice treated with cisplatin-loaded hydrogels exhibited a significant decrease in tumor growth, along with lower plasma AFP levels as compared to hydrogel-treated and untreated tumor-bearing mice." (PMID 33685316, 2021). "In the present study, our model revealed that several predictors, namely, tumor sizes, AFP level, and the number of lesions were strong predictors, consistent with previous studies." (PMID 33738252, 2021). "Vascular invasion is known to be a predictor of early HCC recurrence and is related to AFP, tumor size, and tumor number." (PMID 33974527, 2021). "As such, the present study examined the inter-play of serum AFP (i.e., tumor biology) and HCC TBS (i.e., tumor morphology) by investigating four groups of patients: low–medium TBS/low AFP, low–medium TBS/high AFP, high TBS/low AFP and high TBS/high AFP." (PMID 33670174, 2021). "Our results also show the improved performance of PIVKA-II compared to AFP as a biomarker of tumour response." (PMID 34853657, 2021). "Regarding PFS, age ≤ 60 years, intrahepatic maximal tumor size ≤5 cm, extrahepatic metastasis, Child–Pugh class A, and AFP levels ≤1000 ng/mL were significant factors in univariate analyses." (PMID 34575160, 2021).
tumor (continued). "In this study, high ELF3-AS1 expression in HCC was associated with the characteristics including T stage, gender, residual tumor, histologic grade, adjacent hepatic tissue inflammation, AFP, and vascular invasion." (PMID 34336727, 2021). "Tumor-specific marker (CEA/AFP/CA19-9) responses were mixed and correlated to radiological responses after neither ITPP nor chemotherapy." (PMID 34155211, 2021). "According to results of univariate analysis, LNM, nerve invasion, and preoperative AFP were regarded as independent variables, and tumor recurrence was deemed as the dependent variable." (PMID 33478518, 2021). "The common risk factors that were discussed in previous studies included AFP level, maximal tumor diameter, tumor number, macrovascular invasion, histological grade, distribution, and PIVKA-II." (PMID 34798847, 2021). "They used a set of 11 single peptides to detect immune responses against the five tumor-associated antigens SART2, SART3, MRP3, AFP and hTERT and described an RFA-induced increase of IFN-y producing tumor-specific T cells for all of these peptides." (PMID 33006650, 2021). "MiR-522-3p expression was significantly correlated to AFP (P = 0.012), tumor size (P = 0.004), tumor multiplicity (P = 0.017) and TNM stage (P = 0.002)." (PMID 34666613, 2021). "Current research suggests that molecular tumor markers (TM) can play a crucial role for diagnosis and prognostic evaluation of malignancies, and TM such as AFP, CEA, CA19-9 have been reported in many malignant diseases." (PMID 33727662, 2021). "A recent analysis of the molecular profiles of patients with HCC (n = 520) from two independent cohorts, confirmed the aberrant tumor overexpression of AFP in patients with serum concentrations >400 ng/mL (AFP-high tumors)." (PMID 34298750, 2021). "For example, there are two well-known oncofetal proteins, Carcinoembryonic antigen (CEA) and alpha-fetoprotein (AFP), which originate within tumor cells and enter the bloodstream either by secretion from the tumor or as a breakdown product of tumor cells." (PMID 33966049, 2021). "Multivariate analysis showed that AFP > 400 ng/mL, γ-GT > 54 U/L, multiple tumors, tumor diameter and presence of MVI were identified to be independent risk factors of OS and DFS (all P < 0.05)." (PMID 34663242, 2021). "These include alpha-fetoprotein (AFP) or beta-human chorionic gonadotropin elevation after chemotherapy or incomplete tumor resection in the postoperative period, tumor viability in the pathology specimen after surgery, and induction chemotherapy." (PMID 35047390, 2021). "Our statistical analysis of 642 HCC patients revealed six independent predictive factors for MVI in HCC, particularly Edmondson-Steiner grade, capsule invasion, BDTT, AFP, tumor size, and NLR." (PMID 34869551, 2021). "For those unresectable tumors, TACE has been the preferred treatment, this model is based on levels of albumin, AFP, and tumor diameter and number." (PMID 33835138, 2021). "The independent variables correlated with survival were largest tumor diameter, tumor number, mPVTT extension, and AFP." (PMID 34513667, 2021). "We found that for OS, AFP, tumor number, microvascular invasion, TNM, and serum OPG level still had prognostic significance." (PMID 34650917, 2021). "AFP produced by the tumor itself that leads to an increase in the serum, and sAFP loses its source after tumor resection and then rapidly decreases, similar to our result." (PMID 34706681, 2021). "CK19 presence was related to elevated preoperative alpha fetoprotein (AFP) levels (P = 0.019), poor tumor differentiation (P = 0.007), and microvascular invasion (P = 0.034)." (PMID 34785656, 2021). "In patients with tumor recurrence, the percentage of AFP levels < 10 ng/mL was 35.7% (15/42) and 27.1% (16/59) in group 1 and group 2, respectively." (PMID 34649509, 2021).